MYCN (MYCN proto-oncogene, bHLH transcription factor)
Description:
Positively regulates the transcription of MYCNOS in neuroblastoma cells.
Synonyms: bHLHe37; NMYC; N-myc; MYCNOT; FGLDS1; MODED; MPAPA; MYCNsORF; MYCNsPEP; ODED
Tractability: Small molecule: a structure with a bound ligand is known. PROTAC: ubiquitination databases record sites on it.
Target class: Transcription factor
Gene: Protein-coding gene on chromosome 2 (15,938,396 to 15,947,022, forward strand). Ensembl gene ENSG00000134323.
Subcellular location: Nucleus
Subcellular location (Human Protein Atlas): Nucleoli; Nucleoplasm
Pathways (Reactome):
Signal Transduction: Signaling by ALK; TGFBR3 expression
Cell-Cell communication: Regulation of CDH1 mRNA translation by microRNAs
Immune System: Regulation of PD-L1(CD274) transcription
Gene Ontology:
Molecular function: DNA-binding transcription activator activity, RNA polymerase II-specific; kinase binding; protein binding; RNA polymerase II cis-regulatory region sequence-specific DNA binding; sequence-specific double-stranded DNA binding; DNA binding; DNA-binding transcription factor activity; DNA-binding transcription factor activity, RNA polymerase II-specific; protein dimerization activity
Biological process: negative regulation of gene expression; positive regulation of DNA-templated transcription; positive regulation of gene expression; positive regulation of transcription by RNA polymerase II; positive regulation of miRNA transcription; regulation of transcription by RNA polymerase II; negative regulation of reactive oxygen species metabolic process; regulation of DNA-templated transcription
Cellular component: Myc-Max complex; nucleus; chromatin; nucleoplasm
Genetic constraint (gnomAD): Loss-of-function variants: 3 observed, 24.94 expected, observed/expected ratio (o/e) 0.12, 90% interval 0.054 to 0.31. The synonymous counts are far from expectation, so gnomAD's model fits this gene poorly and the ratio says little. Missense variants: 572 observed, 577.33 expected, observed/expected ratio (o/e) 0.99, 90% interval 0.92 to 1.06. Synonymous variants: 326 observed, 259.97 expected, observed/expected ratio (o/e) 1.25, 90% interval 1.14 to 1.37.
Gene-disease validity (ClinGen):
ClinGen rates the evidence that MYCN causes each of these diseases.
Feingold syndrome type 1 (autosomal dominant): Definitive. Feingold syndrome type 1 (FS1) is a rare inherited malformation syndrome characterized by microcephaly, short stature and numerous digital anomalies.
megalencephaly-polydactyly syndrome (autosomal dominant): Moderate.
Cancer hallmarks: cell replicative immortality; escaping programmed cell death (promotes); angiogenesis (promotes); genome instability and mutations; escaping immune response to cancer (promotes); proliferative signalling (promotes); invasion and metastasis (promotes); genome instability and mutations (suppresses); change of cellular energetics (promotes)
Homologues: Orthologues: chimpanzee MYCN (99% identical), macaque MYCN (98% identical), dog MYCN (91% identical), pig MYCN (90% identical), rat Mycn (85% identical), mouse Mycn (84% identical), guinea pig MYCN (60% identical), mouse Mycs (56% identical), tropical clawed frog mycn (56% identical), rat Mycs (53% identical), zebrafish mycn (48% identical). Paralogues in human: MYC (38% identical), MYCL (31% identical).
Diseases named in the same sentence as MYCN in open-access papers:
MYCN is named in the same sentence as 249 diseases in open-access papers, as found by Europe PMC text mining. Sharing a sentence is not in itself a finding about the gene and the disease. The quoted sentences say what the papers report.
neuroblastoma (2,002 papers, 1989 to 2026). Neuroblastoma (NB) is the most common solid, extracranial childhood tumor. "Amplification of the MYCN oncogene occurs in 20-30% of all neuroblastoma cases and approximately 50% of high-risk tumors, strongly correlating with poor prognosis, relapse, and multidrug resistance." (PMID 41750126, 2026). "High-risk neuroblastoma is characterized by MYCN amplification and high MYCN or MYC gene expression." (PMID 41940329, 2026). "Combined, these results highlight the importance of the PP2A tumor suppressor in regulating MYCN oncogenic signaling and open new potential treatment regimens for high-risk neuroblastoma patients." (PMID 41707997, 2026). "These innovations hold significant promise for improving clinical outcomes in high-risk MYCN-amplified neuroblastoma patients." (PMID 41750126, 2026). "Neuroblastoma is a rare childhood cancer in which high-risk disease, frequently driven by MYCN amplification, has poor survival." (PMID 41876468, 2026). "High-risk neuroblastoma (HRNB) constitutes approximately 50-60% of all neuroblastoma cases and is associated with poor prognostic indicators such as MYCN amplification, metastatic disease, and unfavorable histology." (PMID 40104501, 2025). "The highly aggressive nature of neuroblastoma, including its rapid progression in early childhood, has been associated in previous studies with MYCN amplification, a well-established marker of poor prognosis." (PMID 40963964, 2025). "Currently, the International Neuroblastoma Risk Group (INRG) system has integrated factors such as MYCN amplification, patient age, tumor stage, and ploidy to guide NB treatment." (PMID 40302936, 2025). "The tumor was also identified as an undifferentiated neuroblastoma with MYCN amplification, which is a recognized risk factor for rupture according to genetic pathology." (PMID 41235320, 2025). "Medulloblastoma, similar to neuroblastoma as a common malignant tumor in children, frequently involves MYCN amplification and is associated with a poor prognosis." (PMID 40701975, 2025). "The best characterized neuroblastoma oncogene is MYCN which is amplified in roughly 20% of high-risk cases, of which less than 50% survive." (PMID 41118218, 2025). "High‐risk neuroblastomas, often associated with MYCN protooncogene amplification, are addicted to polyamines, small polycations vital for cellular functioning." (PMID 39981745, 2025). "MYCN is the hallmark oncogene of neuroblastoma and is a prognostic factor that is indicative of unfavorable outcomes in patients with HRNB." (PMID 40104501, 2025). "N-Myc gene (MYCN) amplification occurs in approximately 20% of patients with neuroblastoma, and all patients with MYCN-amplified tumors are classified as high risk with an unfavorable outcome." (PMID 40493396, 2025). "MYCN amplification defines a highly aggressive subtype of neuroblastoma and is strongly associated with poor clinical outcomes." (PMID 41244073, 2025). "Given the central role for MYCN and its target genes in high-risk neuroblastoma, the abrupt and potent depletion of MYCN upon HIF2α induction strongly argues against an oncogenic role for HIF2α in this particular disease." (PMID 41118218, 2025). "The Trump research team identified LRP8, a low-density lipoprotein receptor, as a critical inhibitor of ferroptosis in MYCN-amplified neuroblastoma, with its regulatory mechanism potentially linked to selenocysteine metabolism." (PMID 40108662, 2025). "Approximately 30% of high-risk neuroblastoma cases contain amplification of MYCN, a member of the MYC family of basic helix-loop-helix-leucine zipper (bHLH-LZ) transcription factors." (PMID 40867243, 2025). "In line with that, we observed that EIF4EBP1 mRNA expression in Group 4 MBs is associated with elevated MYCN mRNA expression, as we previously reported in neuroblastoma." (PMID 40670359, 2025).
neuroblastoma (continued). "In high-risk neuroblastoma, there are very few recurrently altered genes: MYCN amplification is the most frequent, detected in 35 % patients." (PMID 39892705, 2025). "Amplified MYCN has been detected in approximately 20% of all neuroblastomas, and is present in about 40% of high-risk neuroblastomas." (PMID 39802403, 2025). "In neuroblastoma, ecDNA promotes high level amplification and extensive intratumoral heterogeneity of the MYCN oncogene, which is associated with poor clinical outcomes." (PMID 41415205, 2025). "These transcriptional changes are accompanied by decreased neuroblastoma cell proliferation and increased neuronal differentiation, reflecting impaired regulation of MYCN target genes upon NIPBL loss." (PMID 40867243, 2025). "NB cases are stratified into low-, intermediate-, and high-risk groups based on several factors: age at diagnosis, MYCN amplification status, International Neuroblastoma Staging System (INSS) stage, histological findings, and tumor cell ploidy." (PMID 41438751, 2025). "ATRX loss-of-function in MYCN amplified neuroblastoma was shown to be synthetically lethal in mouse models and cell lines." (PMID 40286729, 2025). "Previous studies show that neuroblastoma, especially in cases with MYCN amplification, is linked to immunosuppression." (PMID 40552293, 2025). "Aberrant expression of MYCN is associated with the development of various cancers, including neuroblastoma, small cell lung cancer, and other types of tumors." (PMID 40170854, 2025). "Neuroblastoma is a common childhood malignancy, and high-risk presentations, including an MYCN amplified status, continue to result in poor survival." (PMID 40004600, 2025). "Among patients with high-risk neuroblastoma, altered the amplification and expression of the MYCN gene (encoding transcription factor N-MYC) are major hallmarks usually associated with a high risk of recurrence and poor survival." (PMID 41142119, 2025). "SMAD9 is an independent prognostic factor for high-risk neuroblastoma, and its expression is directly regulated by MYCN through SEs." (PMID 41244073, 2025). "50% of high-risk neuroblastomas have MYCN amplification, while the other half express high levels of C-MYC." (PMID 40962798, 2025). "One study has shown that the STK38 modulation of MYCN protein activity and abundance results in the loss of viability of MYCN-amplified neuroblastoma cells." (PMID 41142119, 2025). "Collectively, our results highlight the distinct proliferative and TME characteristics associated with MYCN amplification in neuroblastoma." (PMID 41228227, 2025). "Dysregulation of MYC, such as amplification of MYCN, is associated with tumorigenesis, especially for neuroblastoma." (PMID 39802403, 2025). "Research has demonstrated that MYCN amplification, a genetic alteration associated with aggressive neuroblastoma, leads to increased transcriptional stress and R-loop formation." (PMID 40629041, 2025). "MYCN amplification is present in nearly 40% of high-risk neuroblastomas and is associated with upregulated expression of TERT and telomere dysfunction." (PMID 40115016, 2025). "In neuroblastoma, the oncogene MYCN, a main risk factor of poor prognosis, has been demonstrated to lead to expression changes in numerous glycolytic enzymes." (PMID 40993267, 2025). "Neuroblastoma (NB) with MYCN amplification is strongly correlated with high‐risk stratification and poor prognosis." (PMID 40600620, 2025). "MYCN amplification is a defining feature of high-risk neuroblastoma and drives a transcriptional program that maintains an undifferentiated and proliferative tumor state." (PMID 40867243, 2025). "This dysregulation of MYCN expression is associated with the persistence of undifferentiated and proliferative cells, a histopathological feature of neuroblastoma." (PMID 40365336, 2025).
neuroblastoma (continued). "Pathologic activation of Akt has been shown to frequently occur in neuroblastoma and is associated with a poor prognosis and is possibly related to MYCN amplification." (PMID 40104501, 2025). "Our study reveals that the cohesin loading factor NIPBL plays a pivotal role in maintaining the MYCN-driven oncogenic transcriptional program in high-risk neuroblastoma." (PMID 40867243, 2025). "In this study, we investigate the role of NIPBL in regulating the MYCN–driven transcriptional network in high-risk neuroblastoma." (PMID 40867243, 2025). "Next, patient-derived neuroblastoma cells (PDCs) from patients with high-risk MYCN-amplified neuroblastoma were introduced." (PMID 40493396, 2025). "The review of preclinical data includes a summary of the contribution of polyamine synthetic pathways to high-risk neuroblastoma, the effect that MYCN has on polyamine synthetic pathways, and the proposed mechanism by which DFMO inhibits tumorigenesis." (PMID 40004600, 2025). "Aberrant MYCN activity caused by chromosomal MYCN amplification is a primary driver of high-risk neuroblastoma, which has an overall survival rate of less than 50%." (PMID 41304961, 2025). "Tumor rupture with neuroblastoma is an uncommon but serious complication, particularly in high-risk cases involving MYCN amplification." (PMID 41235320, 2025). "Our findings reveal a critical role for NIPBL in shaping the MYCN-driven transcriptional landscape of high-risk neuroblastoma." (PMID 40867243, 2025). "These cell lines were chosen for our initial study because MYCN amplification is present in ~50% of high-risk neuroblastoma cases." (PMID 40430358, 2025). "In recent years it has become apparent that in neuroblastoma ATRX mutations define a distinct patient subgroup that are mutually exclusive with MYCN amplification, associated with older age at diagnosis and a chronic progressive disease course." (PMID 39892705, 2025). "About 20% of neuroblastomas exhibit amplification of the MYCN oncogene, which is the most well-characterised oncogenic driver and a key indicator of poor prognosis in neuroblastoma, important for risk group stratification in this disease." (PMID 41440947, 2025). "One of the major risk factors in neuroblastoma is the amplification of the MYCN oncogene, observed in around 20%-25% of patients." (PMID 40993267, 2025). "Nearly half (48.1%) of neuroblastoma cases presented with stage IV disease, and 22.2% harbored MYCN amplification, a known poor prognostic factor associated with aggressive clinical behavior." (PMID 41007141, 2025). "Various genetic alterations have been identified in neuroblastoma, including amplification of MYCN, mutations in ALK, and segmental chromosomal changes." (PMID 41536427, 2025). "Eukaryotic translation initiation factor 4E-binding protein 1, a repressor of transcription, is up-regulated by MYCN and is associated with a poor prognosis in neuroblastoma." (PMID 39802403, 2025). "MYCN amplification, a hallmark of high-risk neuroblastoma, was positively correlated with sensitivity to MP1 across tested cell lines." (PMID 41149606, 2025). "Although aberrant expression of MYC is observed in many solid tumors as well as leukemia, MYCN is more commonly associated with neuroblastoma and other neuroendocrine tumors and MYCL is predominantly deregulated in small‐cell lung cancer." (PMID 40488968, 2025). "To understand if CBSIs are broadly effective against neuroblastoma cell lines, we extended our previous cell line paneling to include cell lines marked by genetic risk factors other than MYCN amplification." (PMID 40430358, 2025). "Amplification of MYCN is a hallmark of neuroblastoma and has been the target of several therapeutic strategies." (PMID 39802403, 2025). "Neuroblastoma is a highly aggressive pediatric cancer with a poor prognosis, particularly in high‐risk (HR) cases characterized by MYCN amplification." (PMID 40708972, 2025).
neuroblastoma (continued). "Aberrant expression of MYCN in the developing nervous system has been linked to the development of neuroblastoma and medulloblastoma, highlighting its role as a potent oncogenic driver." (PMID 40365336, 2025). "Our results confirm the well-established association between MYCN, the major key driver of neuroblastoma tumorigenesis, and the poor clinical outcomes in neuroblastoma." (PMID 39860532, 2025). "The expression of MYCN, an established prognostic biomarker for high‐risk neuroblastoma was similarly correlated with poor overall survival and expressed at high levels in late‐stage disease." (PMID 39021294, 2025). "In sum, our data challenge the concept of HIF2α as a neuroblastoma oncogene and show that HIF2α is rather associated with decreased MYCN levels and low-risk tumors as well as noradrenergic chromaffin cell differentiation." (PMID 41118218, 2025). "High-risk neuroblastoma accounts for about 15% of all pediatric cancer deaths, and MYCN oncogene amplification is present in over 30% of high-risk neuroblastomas." (PMID 40548062, 2025). "For instance, tumor cells are more susceptible to GPX4 inhibitors in the therapy of neuroblastoma because of the high expression of the tumor’s own MYCN gene." (PMID 40969276, 2025). "The CDK9/2 inhibitor CYC065 that selectively targets MYCN-amplified neuroblastoma in vitro, caused growth arrest after 48 h and cell death in WT cultures upon prolonged treatment for 5 days." (PMID 39740515, 2025). "Amplification of the MYCN locus is found in around 22% of neuroblastomas, and is strongly associated with advanced stages, rapid tumor progression, and poor clinical outcomes." (PMID 40365336, 2025). "We present a rare case of high-risk MYCN-amplified neuroblastoma in a 4-year-old girl who developed tumor rupture and ACS soon after the initiation of induction chemotherapy that required emergency surgical intervention." (PMID 41235320, 2025). "In pediatric malignancies such as neuroblastoma and medulloblastoma, MYCN amplification is a hallmark genetic feature and has been shown to drive MIR17HG expression." (PMID 41473312, 2025). "Abnormalities in pyrimidine metabolism, which are closely linked to uncontrolled cell proliferation, make DHODH a key contributor to cancer development, particularly in high-risk neuroblastoma, where it is associated with MYCN status." (PMID 40513779, 2025). "We analyzed known checkpoints and surface markers in MYCN-A versus MYCN-NA tumors to identify factors underlying the reduced immune infiltration in MYCN-A neuroblastomas." (PMID 39860532, 2025). "An additional challenge is that embryonal tumours have a low mutational burden and are driven by a few key genetic events (e.g., MYCN amplification in neuroblastoma, RB1 loss in retinoblastoma)." (PMID 41034452, 2025). "Tumor rupture is a rare but life-threatening complication of high-risk MYCN-amplified neuroblastoma and ACS after induction chemotherapy." (PMID 41235320, 2025). "MYCN amplification is a hallmark of aggressive neuroblastoma, driving N-Myc overexpression and enhancing protein synthesis, making these processes potential therapeutic targets." (PMID 39396233, 2024). "MYCN is a transcription factor oncogene and known driver of neuroblastoma associated with high-risk disease and poor overall survival." (PMID 38869684, 2024). "Gain of 17q is the most frequent genetic event in high-risk neuroblastoma and is associated with MYCN amplification." (PMID 38488852, 2024). "Given the large number of genes alternatively spliced in high-risk neuroblastoma patients, we next sought to investigate the changes in the splicing landscape resulting from disruptions to MYCN and SNRPD3 expression." (PMID 38049564, 2024).